INS (insulin)
Diseases named in the same sentence as INS in open-access papers (continued):
Sharing a sentence is not in itself a finding about the gene and the disease.
diabetes (continued). "The demand for health services during adolescence is low, and biochemical assessments, particularly blood glucose, HOMA-IR, and insulin levels, can be important early markers of diabetes." (PMID 36078265, 2022). "Diabetes resulting from insufficient insulin secretion or insulin resistance (IR) is a highly prevalent metabolic disease." (PMID 37529096, 2022). "Although glycaemic control among patients with T2DM was comparable in both EOSS-2 and EOSS-3 groups, EOSS-3 patients had diabetes for longer and more were on insulin therapy." (PMID 35267942, 2022). "The main purpose of insulin therapy in diabetes mellitus is to control glucose—in other words, to combat dysglycemia." (PMID 35802405, 2022). "A potential importance of insulin under these conditions is additionally emphasized by the observation that diabetes mellitus is accompanied by reproductive disorders resulting from impaired LH secretion in rodents." (PMID 36297033, 2022). "Since 1934, when zinc was shown to be a component of insulin crystals, a link between zinc and diabetes has been proposed." (PMID 36352900, 2022). "The risk factors for DME have been widely studied, including duration of diabetes, hypertension, glycosylated hemoglobin (HbA1c) level, insulin, and other factors." (PMID 35937830, 2022). "There are mainly two major types of diabetes, type 1 (destruction of insulin-producing cells in the pancreas) and type 2 (combination of insulin resistance (IR) and insufficient insulin production)." (PMID 35744089, 2022). "DM is chronic hyperglycemia caused by insufficient insulin secretion or increased insulin resistance in the body, including type I (T1DM) and type II (T2DM) diabetes." (PMID 35692502, 2022). "NVC effects of medications such as pioglitazone and GLP-1 receptor agonists with effects on insulin sensitivity and low-activity inflammation commonly used in diabetes also need further exploration." (PMID 35860697, 2022). "FA also has beneficial effects on diabetes by suppressing oxidative stress, increasing plasma insulin levels, and lowering blood glucose." (PMID 36457710, 2022). "Among participants with IGT, insulin resistance, compensated hyperinsulinemia (indicating a high insulin demand) together with the progression to diabetes accelerated the development of cancer." (PMID 35256755, 2022). "More than 2500 miRNAs were identified in the human genome, and several of them were found to be involved in diabetes mellitus pathogenesis, insulin sensitivity, cardiomyocytes hypertrophy, fibrosis and diastolic dysfunction." (PMID 35562979, 2022). "Diabetes mellitus occurs whereby an abnormally high blood glucose level (hyperglycaemia) results from insulin insufficiency, and/or impaired tissue response to insulin (i.e., insulin resistance)." (PMID 36555531, 2022). "So, it is clear that maintaining FBG close to the optimum level and modifying insulin biomarkers, prevents disruption of the lipid profile and can be useful in the treatment of diabetes." (PMID 35655590, 2022). "In the long term, infants of women with diabetes are more likely to be overweight and obese in childhood and display evidence of significant insulin resistance (even when adjusted for confounders like family history)." (PMID 36714590, 2022). "While some were beneficial (i.e., watching for signs of diabetes, providing healthy foods), others were potentially harmful (i.e., limiting contact with other children, administering insulin unnecessarily)." (PMID 36278623, 2022). "We identified the significant T2DM targets of Asian propolis, namely retinol-binding protein-4 (RBP4) and aldose reductase (AKR1B1) that have important roles in insulin sensitivity and diabetes complication, respectively." (PMID 35807241, 2022). "This study was designed to generate functional insulin-producing cells (IPCs) from dental-derived mesenchymal stem cells (MSCs) and further explore their therapeutic potential against diabetes mellitus in vivo." (PMID 35674918, 2022).
diabetes (continued). "Potassium channels are expressed in many tissues, including pancreatic islet cells, and are involved in insulin production and secretion and, thus, in carbohydrate metabolism and the pathogenesis of type 2 diabetes mellitus and GDM." (PMID 35893051, 2022). "For instance, SCFAs have been found to promote the host to secrete glucagon-like peptide-1, which can lower the serum levels of glucose, increase insulin secretion and resistance, and protect pancreatic β-cell function in the treatment of diabetes." (PMID 36548856, 2022). "We recommend screening of the INS gene in all children diagnosed with diabetes in the first year of life." (PMID 35518939, 2022). "Lysophospholipids (namely LPC, LPE), is important for glucose-mediated insulin secretion in diabetes targeting tissues." (PMID 35432194, 2022). "Antithrombotic agents (e.g., warfarin, clopidogrel, and aspirin), drugs used in diabetes (e.g., insulin and oral hypoglycemic agents), and antineoplastic agents were common drugs in preventable ADE related ED visits." (PMID 36121802, 2022). "The aim of the current study is to investigate safety and efficacy of intermittent fasting in people with type 2 diabetes mellitus and insulin therapy compared with usual care." (PMID 35179802, 2022). "Insulin-stimulated GLUT-4 translocation is disrupted in diabetes, and exercise training stimulates the translocation of GLUT-4 to the muscle cell membrane in diabetic patients." (PMID 36213227, 2022). "However, at present there is no satisfactory explanation for how insulin resistance might stimulate insulin secretion, while there are only a few naturally occurring or genetic models of primary insulin resistance, and few diabetes genes are implicated in insulin resistance." (PMID 35897752, 2022). "Other risk factors reported to be associated with PAH include hypertension, abnormal lung function, diabetes, uric acid level, age, insulin status, obesity, thyroid problems, and female sex hormones." (PMID 35457576, 2022). "Diabetes mellitus is a severe disease characterized by high blood glucose levels resulting from dysregulation of the hormone insulin." (PMID 36018623, 2022). "Further complicating the issue of prescription medications, respondents from seven communities identified power outages as a barrier to storing refrigerated medications, especially insulin for diabetes management." (PMID 36380330, 2022). "Generally, in patients affected by chronic kidney disease (CKD) and diabetes, decreased insulin secretion and increased insulin resistance is reported with a consequent increase in the glycemic values." (PMID 35329847, 2022). "Our results show a late postoperative diagnosis rate of diabetes mellitus (> 30 days) in 22.2% (n = 4) of the patients who were taken to the PF in a mean follow-up of 42.5 months; nonetheless, any patient required insulin replacement." (PMID 36503674, 2022). "Children whose diabetes was managed with a insulin pump scored higher on self-esteem general and social than those whose diabetes was managed by insulin injection." (PMID 36508408, 2022). "Subjects with impaired glucose homeostasis (prediabetes) and diabetes are largely at the lower left edge of this hyperbolic region, indicating comparatively lower functional capacity of beta cells and/or insulin sensitivity." (PMID 36271244, 2022). "Further studies suggest that ebselen ameliorates lipotoxic dysfunction by inhibiting oxidative stress and preserving insulin secretion and β-cell mass in Zucker diabetic models, as well as in other experimental diabetes models." (PMID 36430158, 2022). "Pancreatic β-cell XAF1 expression was enhanced via HFD-induced, macrophage-derived IFNβ, which promoted β-cell apoptosis and led to a reduction in insulin secretion and progression of diabetes." (PMID 35829914, 2022). "In biological mechanisms, insulin resistance, insulin sensitivity, and metabolic syndrome were all the important triggers of diabetes." (PMID 35559347, 2022).
diabetes (continued). "Type 2 diabetes mellitus (T2DM) is a long-term metabolic disorder characterized by hyperglycemia, insulin resistance, and relative deficiency of insulin." (PMID 35126820, 2022). "Still, trials are in progress to further improve insulin treatment against diabetes (such as the introduction of commercial pancreases)." (PMID 35723344, 2022). "Six studies defined T2DM as abnormal laboratory tests (HbA1c or fasting blood glucose), self-reported physician-diagnosed diabetes, or use of oral hypoglycemic medications or insulin." (PMID 35805265, 2022). "As expected, upon induction of KATP-GOF expression by tamoxifen, NDM mice developed severe diabetes and a marked decrease in plasma insulin levels." (PMID 35180212, 2022). "According to studies, periodontal disease in children with diabetes appears to progress around puberty because puberty adversely impacts insulin action and HbA1c control." (PMID 36384715, 2022). "Understanding the environment necessary for beta cell survival and proper insulin secretion is necessary for the generation of effective and long-lasting diabetes therapies." (PMID 35769082, 2022). "The insulin-sensitizing effects of SERCA2 are fascinating as a drug target for diabetes with the aim of improving insulin sensitivity." (PMID 35563793, 2022). "In pre-diabetes, the strongest correlation between insulin iAUC0-10 and CP iAUC0-10 was identified for AUC (CP0-60)/AUC (G0-60), CP30, CP60/G60, and CP30/G30." (PMID 36100292, 2022). "Twenty years ago, available classes of antidiabetic medicines were limited to insulin, biguanides and sulfonylureas, but in the last decade, newer insulin derivatives and classes of antidiabetic medicines have been approved for the treatment of diabetes." (PMID 36243730, 2022). "Physical activity can be limited by physiological conditions, such as neuropathy, foot ulcers or heart disease, and weight gain can be attributed to certain diabetes medications such as insulin." (PMID 36232191, 2022). "In the current study, given the longer diabetes duration and higher glycemia in insulin-treated subjects, prior insulin treatment probably rests the beta-cell to facilitate the glycemic effects of GLP-1 RAs." (PMID 36559020, 2022). "These mice also had diabetes, fatty liver, and higher levels of TGs, insulin, and glucose in plasma." (PMID 36354755, 2022). "Diabetes mellitus is a medical condition that results from the inability of the pancreas to produce enough insulin or the body’s inability to effectively use the insulin produced, and can be classified as type 1, type 2, and gestational diabetes." (PMID 36551155, 2022). "During this therapy a near normalization of glycaemia by insulin leads to the remission of diabetes mellitus, constituting an improvement of own insulin secretion and a reverse of insulin resistance, both of which make stopping of insulin regimen possible." (PMID 36670938, 2022). "Many studies have used SGLT2 as a molecular target to specifically inhibit SGLT2, which has become a new approach to insulin-independent treatment of diabetes." (PMID 36035950, 2022). "Type 1 diabetes mellitus (T1D) is a chronic disease that requires lifelong insulin replacement therapy." (PMID 36528643, 2022). "Experiences gathered include new pharmacy operation workflows, the clinical role of pharmacy services, introduction of remdesivir treatment, and pharmacy involvement in newly diagnosed diabetes patients requiring insulin teaching." (PMID 35601713, 2022). "In Ethiopia, children and adolescents with diabetes receive donated insulin and blood glucose test strips." (PMID 35705956, 2022). "Patients with T2DM rely on a complexity of diabetes therapeutic schedule (e.g., a combination of multiple drugs and/or insulin therapy) to achieve glycemic control." (PMID 36600932, 2022).
diabetes (continued). "Specifically, DPP4 inhibitors have been shown to mitigate endoplasmic reticulum stress, which often occurs in the beta cells of patients with diabetes, while also aiding in insulin production to compensate for this stress." (PMID 35229479, 2022). "Diabetes mellitus (DM) is a metabolic disease characterized by hyperglycemia due to the impairment in insulin secretion or insulin resistance." (PMID 36992724, 2022). "Prior clinical research reported that a minimum of 5 g to 10 g of d-allulose before carbohydrate loading is sufficient to reduce postprandial blood glucose levels, insulin levels, and glucose iAUCs among pre-diabetes individuals and diabetic patients." (PMID 35729673, 2022). "The first description of a failed suicide attempt with exogenous insulin appears in literature in 1927, which is a few years after insulin was introduced into the treatment of diabetes in 1921." (PMID 35324747, 2022). "All of the patients with diabetes were insulin treated, and 3 had experienced diabetic ketoacidosis." (PMID 35552684, 2022). "Peripheral administration of IL-6 in mice induces insulin resistance, and peripheral IL-6 antibody neutralisation of IL-6 in a transgenic diabetes mouse model improves hepatic insulin sensitivity." (PMID 35470093, 2022). "The reduction in insulin production can then accelerate pre-existing DM and induce hyperglycemia or even new onset diabetes in previously normoglycemic subjects." (PMID 36992740, 2022). "Upon systemic delivery, the AAV8 vector successfully showed treatment efficacy and potentially served as future long-term basal insulin gene therapy for diabetes patients." (PMID 35105948, 2022). "Previous studies found that DDB1-mediated degradation of Cry1 was an important target for insulin action on glucose homeostasis, and the FUT8 was strongly associated with increased susceptibility to diabetes." (PMID 36360309, 2022). "Diabetes-related death among people younger than 25 years, principally due to incomplete or inadequate access to basic health care for type 1 diabetes, can be largely avoided with universal access to insulin and basic diabetes care." (PMID 35143780, 2022). "Porcine and SC-beta islets made insulin in xenotransplant models, and mouse islets tested in a marginal mass syngeneic transplant model cured diabetes in 92% of recipients within 24–48 h after transplant." (PMID 35288694, 2022). "Rapamycin and metformin combination treatment in a mouse model of type 2 diabetes, NONcNZO10/LtJ males, prevents hyperinsulinemia, normalizes insulin sensitivity, and reduces pathological complications of diabetes." (PMID 35986566, 2022). "The majority of diabetic cases were insulin-dependent and all patients had poor diabetes control (mean glycated haemoglobin level = 9.7)." (PMID 36611916, 2022). "The utilized algorithms for the prediction of BG are critical in the progress of closed-loop insulin delivery and decision support systems for the control of blood glucose in diabetes." (PMID 36572938, 2022). "With respect to oral drugs and/or insulin for the treatment of diabetes, the highestproportions of medication obtainment through the PFPB were identified in EspíritoSanto, Rio Grande do Sul, and Goiás." (PMID 35830016, 2022). "Under certain circumstances, such as carbohydrate-restrictive diets, starvation, prolonged intense exercise, alcoholism, low food intake, insulin resistance, or diabetes mellitus, the liver produces ketone bodies by utilizing fatty acids." (PMID 36135388, 2022). "At present, the U.S. Food and Drug Administration (FDA) has approved more than 100 types of insulin products for the clinical treatment of diabetes." (PMID 35328783, 2022). "Study participants shall be randomised to one of the study arms using minimisation on age (18–40 years; 41–60 years), gender, duration of diabetes (≤ 5 years; > 5 years), and medications (oral + basal insulin; oral + basal/bolus insulin)." (PMID 35710428, 2022).
diabetes (continued). "Most taxa in the region are used in traditional medicine to prevent or treat diabetes mellitus, a group of metabolic diseases characterized by hyperglycemia resulting from defects in insulin secretion, insulin action or both." (PMID 36616160, 2022). "Individuals with longer durations of diabetes often decreased their carbohydrate-to-insulin ratio on race day, taking more insulin, than on the training day while the reverse was noted for those newly diagnosed (r = -0.52, p = 0.05)." (PMID 36992757, 2022). "There are also a large number of animal experiments revealing that Galectin-3 promotes the inflammation of pancreatic islet β cells and insulin target organs, leading to pancreatic β cell failure and insulin resistance, which in turn leads to diabetes." (PMID 35083706, 2022). "A few reviews have analyzed both glycemic control and adverse events during Ramadan for insulin-requiring diabetes, specifically." (PMID 35634376, 2022). "Among LDP patients, 4 patients with preoperative diabetes mellitus needed to maintain the blood sugar level by increasing insulin injection dosage after operation, and 11 patients had new-onset diabetes mellitus." (PMID 35024102, 2022). "The most frequent (up to 50% of patients) metabolic disorders in acromegaly resulting from direct anti-insulin effects of GH is insulin resistance leading to glucose intolerance and diabetes mellitus (DM)." (PMID 34498217, 2022). "The most common predictors of hypoglycaemia were pre-treatment serum glucose concentration (n = 13 studies), insulin dose (n = 8 studies), kidney failure (n = 5 studies) and diabetes (n = 4 studies)." (PMID 35552566, 2022). "In Tobit regression models, longer duration of diabetes, uncontrolled blood sugar level, insulin usage, obesity, and presence of diabetic-related complications were negatively associated with EQ-5D-5L utility and EQ-VAS scores." (PMID 35180266, 2022). "Mobile apps and web-based platforms provide many options for managing diabetes, including blood glucose tracking, insulin dosing, and diabetes education." (PMID 35019844, 2022). "The current study evaluated the impact of SG-loaded SEEDS on glucose homeostasis and insulin regulation in order to better understand the role of SG in diabetes management." (PMID 35624887, 2022). "In CD38 autoantibodies found in diabetes patients, some autoantibodies show agonistic effects on insulin secretion and others show antagonistic effects." (PMID 35457121, 2022). "When people with diabetes require insulin, it is given as a subcutaneous injection in a manner that exposes the insulin receptor to a constant level of insulin." (PMID 35163806, 2022). "On the other hand, insulin therapy is a common method to treat diabetes that involves regulating glucose and lipid metabolism." (PMID 35311032, 2022). "The discovery of insulin by Banting and Best in 1921 heralded a breakthrough for diabetes treatment, with the first human to receive insulin treatment in 1922." (PMID 34991585, 2022). "Excessive accumulation of unfolded or misfolded proteins can cause ER stress, which triggers the death of pancreatic islet β-cells and insulin resistance in skeletal muscle and the liver in diabetes." (PMID 36358477, 2022). "Diabetes treated with insulin (p < 0.001), chronic kidney diseases (CKD) (p = 0.004) and chronic coronary syndrome (CCS) (p < 0.001) with myocardial infarction (MI) (p = 0.005) were most frequent in the CFS 4–6 group." (PMID 35162123, 2022). "Our previous study showed that immediate blood sugar control with insulin treatment after AION induction in mice with STZ-induced diabetes reduced damage to the retinal structure." (PMID 36613856, 2022). "Insulin edema rarely occurs with initiation or intensification of insulin treatment in people with diabetes." (PMID 36180933, 2022).